RNU6-302P (RNA, U6 small nuclear 302, pseudogene)
Gene: Small nuclear RNA gene on chromosome 6 (150,939,222 to 150,939,328, forward strand). Ensembl gene ENSG00000202119.
Homologues: Orthologues: macaque U6 (94% identical), chimpanzee U6 (93% identical), rabbit U6 (79% identical), rabbit U6 (78% identical), rabbit U6 (77% identical), guinea pig U6 (76% identical), guinea pig U6 (72% identical). Paralogues in human: RNU6-1209P (84% identical), RNU6-1309P (84% identical), RNU6-204P (84% identical), RNU6-454P (84% identical), RNU6-130P (83% identical), RNU6-86P (83% identical), RNU6-1094P (82% identical), RNU6-480P (82% identical), RNU6-560P (82% identical), RNU6-11P (81% identical), RNU6-1310P (81% identical), RNU6-144P (81% identical), and 1287 more.